BRAF (B-Raf proto-oncogene, serine/threonine kinase)
Diseases named in the same sentence as BRAF in open-access papers (continued):
Sharing a sentence is not in itself a finding about the gene and the disease.
tumor (continued). "For patients with RAS and BRAF mutations, triplet chemotherapy and combinations with bevacizumab represented two rational alternatives on the basis of high response rates and tumor shrinkage; however their efficacy in the conversion setting has yet to be confirmed in specifically designed studies." (PMID 27248177, 2016). "Of the 15 patients whose tumor could be assessed for BRAF mutation status, 10 (67 %) patients had wild-type BRAF, and 5 (33 %) patients had a BRAF V600E mutation." (PMID 27056178, 2016). "A multivariate Cox analysis for the 200 CRC showed that the 6-GPS remained significantly associated with patients' RFS (HR=3.05; 95% CI: 1.66–5.60; P-value=3.36E-04), after adjusting for tumor stage, gender, age, tumor location, mismatch repair status and gene mutation (BRAF and KRAS)." (PMID 27429074, 2016). "BRAF mutations were present in nine patients (6%), all of whom had tumours that were WT for RAS." (PMID 27764839, 2016). "In order to investigate the evolution of the NRAS/BRAF double mutated cancer cells within a patient, we analyzed tumor DNA for the presence of double mutations in all available histological and frozen material from patients 4, 5, 6, 7 and 8 before and after BRAF inhibitor treatment." (PMID 27791198, 2016). "Only one tumor harboring complex BRAF/NRAS mutations showed weak tumor regression (−24%)." (PMID 26989027, 2016). "Particularly relevant for future applications, this tumor/normal cell lines contains hallmark clinically relevant mutations spanning different mutation classes, including a BRAF V600E SNV, a PTEN 12 kb focal deletion, a TERT dinucleotide block substitution, and a 2 bp small deletion in CDK2NA." (PMID 27094764, 2016). "Therefore, the effect of shifting tumor metabolism in the direction of oxidative metabolism as a result of the BRAF-V600E mutation makes the tumor more responsive to LND and agents that it potentiates such as N-mustards and anthracyclines." (PMID 27285585, 2016). "We hypothesized that, using digital PCR (DigPCR) technology to detect BRAF mutations, tumor-derived cfDNA could be quantified in the CSF in these patients with CNS involvement and that the level of tumor-derived cfDNA would correlate with disease burden." (PMID 27863426, 2016). "Abnormal activation of this pathway, for example by BRAF mutation, results in the disruption of biological homeostasis and may result in tumor transformation." (PMID 27600854, 2016). "BRAF V600E mutation is associated with the tumor susceptibility BRAF targeted therapy." (PMID 27597976, 2016). "Of note, the broad distribution of the WT allele (blue line) included a substantial proportion of overlapping fragment sizes with the mutant allele since the BRAF V600E mutation is heterozygous and tumor cells also introduced shorter fragment lengths into the circulation with the WT allele." (PMID 27428049, 2016). "Tumor tissue-based driver mutations in genes like BRAF or MITF might be of high impact for the treatment outcome of targeted therapies, but do not correlate with chemotherapy outcome." (PMID 26799424, 2016). "Furthermore, it provides more results to support the involvement of IL-6 in tumor-promoting inflammation in this malignancy, and the data also suggest that IL-6 interacts differentially with the tumorigenic mechanisms of mutated BRAF and RAS in CRC." (PMID 27738330, 2016). "In the presence of PTEN/BRAF mutations activated β-catenin drives highly metastatic tumours." (PMID 27531891, 2016). "In contrast, BRAF mutations were detectable in all of the papCP tumor samples." (PMID 26927026, 2016). "Likewise, if only the invasive adenocarcinoma, solid predominant nodule, had been tested, we would have believed that both tumor nodules contained the identified BRAF mutation." (PMID 27597976, 2016).
tumor (continued). "“Classical” BRAF mutations (substitutions in codons 600 and 601) are associated with tumor cell sensitivity to BRAF inhibitors: most commonly used of them are vemurafenib and dabrafenib, whereas other are also known: encorafenib, and experimental XL281 (Exelixis), CEP-32496." (PMID 27276710, 2016). "The prognostic significance of CIMP is currently undefined and may be modified by MSI status, presence of BRAF mutation, tumor stage, or other factors." (PMID 26884349, 2016). "By isolating and sequencing colonies derived from 23 single-cell clones of the resistant late metastasis 6 from patient 1, we could show for the first time that both activating MAPK mutations (NRAS and BRAF) were present in a single tumor cell." (PMID 27791198, 2016). "This fact suggests that in patients with BRAF mutation, SL/Bev may have potent anti-tumour activity based on some specific effects." (PMID 26311588, 2015). "In principle, treating patients harbouring subclonal BRAF mutations with BRAF inhibitors may stimulate the growth of BRAF-wild-type tumour cells." (PMID 25894462, 2015). "Moreover, miR-378-5p was negatively associated with BRAF in CRC tissues compared to adjacent non-tumor tissues." (PMID 25977643, 2015). "In these patients the data suggest that the mutated BRAF gene, present in 5–10% of the tumours, may affect the response to these agents." (PMID 25932044, 2015). "In a separate set of 100 FFPE tumor samples (64 with BRAF mutation per Idylla), the Idylla and CLIA-certified laboratory results demonstrated an agreement of 96% even though the tests were not performed simultaneously and different FFPE blocks had to be used for 9 cases." (PMID 26330075, 2015). "KRAS p.G12V and BRAF p.V600E mutations occurred together in a further tumor sample." (PMID 25568935, 2015). "Furthermore, we found a BRAF V600K mutation in cfDNA in 4 patients with wt BRAF in their tumor tissue." (PMID 25980577, 2015). "Tumors with BRAF or KRAS mutations were in correlation with elevated serum level of tumor biomarkers of CRC and the combination of serum biomarkers and molecular mutation status may enhance the more precise risk stratification of CRC patients." (PMID 26530529, 2015). "However, recent studies show that metastases of CRC rarely contain BRAF mutation with BRAF wild-type primary tumours." (PMID 25977643, 2015). "Future larger studies are warranted to establish whether finding a BRAF mutation in a smaller tumor correlates with more aggressive disease." (PMID 26448939, 2015). "The same trend for dissemination can be seen for BRAF wild type tumours with a KRAS mutation." (PMID 25884297, 2015). "The BRAF mutated tumour showed strong cytosolic and membranous positivity for B-Raf." (PMID 26197800, 2015). "Future studies are warranted to establish whether finding a BRAF mutation in a smaller tumor has clinical significance." (PMID 26448939, 2015). "However, since BRAF mutations are strongly associated with sessile serrated phenotypes, their individual effects as tumor initiators in the intestinal epithelium are clearly different." (PMID 26299805, 2015). "BRAF mutation is associated with the serrated tumour phenotype." (PMID 26097884, 2015). "The serrated pathway is characterized by an epigenetic mechanism that involves abnormal methylation of CpG islands in the promoter regions of tumor suppressor genes and may be associated with mutations of the BRAF oncogene." (PMID 25977829, 2015). "The present study revealed that PIK3CA mutations were more common in MSI and BRAF mutated tumours." (PMID 25884297, 2015). "Similarly, BRAF (v-Raf murine sarcoma viral oncogene homolog B1) mutation can also drive tumor development in NSCLC." (PMID 25706985, 2015).
tumor (continued). "For such patients, the clinical benefit of diagnosing a BRAF mutation in a very small fraction of the tumour cells may be questioned." (PMID 25318602, 2015). "The observed phenomenon whereby BRAF mutated tumours demonstrate resistance to 5-FU-based chemotherapy may be associated with the phenomenon of differential changes in TFAP2E promoter methylation." (PMID 26097884, 2015). "Now, in the case of BRAF-mutated tumor, they can receive vemurafenib (anti-BRAF target drug) and have ∼50% chance of response, or, irrespectively of BRAF mutation, ipilimumab (immune checkpoint inhibitor) with ∼20% chance of long-term (>5 years) disease control." (PMID 26320181, 2015). "For several years, Sanger sequencing has been considered the reference method for detection of specific mutations in human tumours, including BRAF V600E and V600K, although a “gold standard” detection method for these mutations in diagnostic laboratories is yet to be established." (PMID 25318602, 2015). "The evolutional conservation of the BRAF V600E mutation highlights the importance of MAPK pathway activation in neoplasia and may offer opportunity for molecular diagnostics and targeted therapeutics for dogs bearing BRAF-mutated cancers." (PMID 26053201, 2015). "The BRAF V600E mutation was found in both FFPE tumor and plasma specimens from one patient." (PMID 25954997, 2015). "Patient 8 had NRAS mutation Q61K in approximately 94% of tumor cells and BRAF V600E in 4%." (PMID 25794135, 2015). "In addition, BRAF-mutated carcinomas were significantly associated with larger tumor size compared with wild-type BRAF tumors (5.83 ± 2.13 vs 4.87 ± 1.89; P = 0.004)." (PMID 25929517, 2015). "An interesting aspect of BRAF V600E is the fact that several biphasic tumors have been reported with this mutation, suggesting that perhaps this mutational underpinning allows for emergence of additional tumor components." (PMID 24321241, 2014). "Moreover, high bodyfat percentage was significantly associated with an increased risk of BRAF wild type tumours (ptrend = 0.032)." (PMID 24918610, 2014). "BRAF mutations in exon 15 were found in 9 out of 214 (4.2%) tumor samples." (PMID 25367198, 2014). "We examined KRAS mutations in codons 12, 13, 61 and 146 (assessed by pyrosequencing), in relation to clinicopathological features, and tumor molecular markers, including BRAF and PIK3CA mutations, CpG island methylator phenotype (CIMP), LINE-1 methylation, and microsatellite instability (MSI)." (PMID 24885062, 2014). "All of these mutations are able to hyperactivate BRAF protein causing tumor progression or inducing features of aggressiveness, ultimately leading to the diminished or nule expression of several thyroid-specific genes, radioiodine uptake, and pronounced hypothyroidism." (PMID 25328756, 2014). "Further, 423 (85.6%) of the tumours were BRAF wild type, and 71 (14.4%) were BRAF-mutated." (PMID 24918610, 2014). "Furthermore, transition/transversion analysis led to a novel finding that tandem CC>TT/GG>AA mutations (UV damage signature) were more common in tumours arising in severely sun damaged skin and in BRAF/NRAS wild-type tumours." (PMID 24752294, 2014). "Six studies reported the association between BRAF mutation and tumor histology." (PMID 24979348, 2014). "In summary, BRAF mutations appear to occur more frequently in CRC tumours with MSI-high characterised by dMMR, posing as strong OS prognostic factor, but also presence of KRAS mutations in patients proficient in MMR may suggest highest recurrence rate." (PMID 25361007, 2014). "In addition, the MAP kinase pathway is already engaged due to the KRAS or BRAF mutations in the tumor cell lines used in this work." (PMID 25285080, 2014).
tumor (continued). "Methylation data was analysed using a recursively partitioned mixture model and investigated for associations with clinicopathological and molecular features including age, Helicobacter pylori status, tumor site, patient survival, microsatellite instability and BRAF and KRAS mutations." (PMID 24674026, 2014). "BRAF V600E mutation, as seen here, indicates a sporadic tumor." (PMID 25338547, 2014). "In addition, significant correlations were observed between the BRAF mutation and age (>45 years), tumor-lymph node-metastasis stage and tumor persistence/recurrence." (PMID 24396464, 2014). "In vivo, AZD6244 could inhibit the tumor growth in HT-29 xenograft model, which is a colorectal tumor model carrying a BRAF mutation, at a dose of 100 mg/kg and the tumor growth inhibition of AZD6244 is better than gemcitabine." (PMID 24939055, 2014). "Because the tumor possessed two geographically distinct areas of PXA versus epithelioid neuronal tumor, samples could be tested separately and confidently from these two differing areas of tumor for BRAF V600E mutational status." (PMID 24321241, 2014). "Mutations in the BRAF gene were closely related to particular demographic or clinicopathologic characteristics, including smoking habits, gender, clinical stage, differential and tumor histology." (PMID 24979348, 2014). "In conclusion, the results from this prospective study provide further support to the accumulating evidence of the influence of lifestyle factors and sex on different pathways of colorectal carcinogenesis, defined by KRAS and BRAF mutation status of the tumours." (PMID 24918610, 2014). "Two previous studies have investigated the association between BMI and BRAF status in CRC tumours." (PMID 24918610, 2014). "Similarly, a poorer survival of metastatic patients with BRAF or NRAS tumor mutations and of patients with BRAF-mutant tumors after treatment with temozolomide and bevacizumab was reported before." (PMID 24586605, 2014). "BRAF mutations seem to occur more frequently in CRC tumours with MSI-high characterised by dMMR, and poses as strong OS prognostic factor, however presence of KRAS mutations may suggest highest recurrence rate." (PMID 25361007, 2014). "Moreover, we reasoned that it is of particular interest to identify which tumor cells in the primary lesion have the highest metastatic capabilities and associate them with the presence of mutant BRAF." (PMID 25526463, 2014). "Similarly, a worse prognosis of metastatic patients with BRAF or NRAS tumor mutations and of patients with BRAF mutant tumors after treatment with temozolomide and bevacizumab was reported before." (PMID 24475086, 2014). "Only one BRAF L588F missense mutation was identified in these tumor samples." (PMID 25198510, 2014). "Thus for now, therapy should be individualized based on the tumor’s BRAF mutational status, disease burden, performance status, and comorbidities." (PMID 26328215, 2014). "It was observed that the BRAF V600E mutation was associated with age, tumor stage and prognosis." (PMID 24396464, 2014). "Mutated forms of BRAF, including V600E, result in a constitutively activated BRAFkinase that may stimulate tumor growth." (PMID 25089220, 2014). "The tumor unexpectedly contained a BRAF V600E mutation, CDKN2A loss and PTPRD S1845fs*2 mutation." (PMID 25563358, 2014). "Mutations in BRAF or PIK3CA showed a significant correlation with tumor location." (PMID 25367198, 2014). "While this could indicate tumor hypomethylation in BRAF wildtype samples compared with normal and BRAF mutated samples, the high level of chromosomal instability among BRAF wildtype samples suggests that copy-number loss is the most plausible explanation." (PMID 23324568, 2013). "BRAF mutation at codon 600 analysis was performed in 83/95 tumor specimens." (PMID 23637996, 2013). "Patients with BRAF-mutated tumours had worse overall survival than did all-wild-type patients." (PMID 23725851, 2013).
tumor (continued). "One BRAF mutation, p.Val471Ala, occurred in a tumor also carrying a PIK3CA p.His1047Arg mutation." (PMID 23548132, 2013). "A close association between BRAF mutation and aberrant methylation of several tumor-suppressor genes in PTC, including the genes for tissue inhibitor of matrix metalloproteinase-3 (TIMP3), death-associated protein kinase (DAPK), and retinoic acid receptor β2 (RARβ2) has been reported." (PMID 24868250, 2013). "Indeed, TSC22 family members have been shown in Drosophila to be part of a growth-promoting signaling complex involving the Mlf1 adapter molecule Madm, and a TSC22D1/D4 complex has been implicated in BRAF-induced senescence and neoplasia." (PMID 23307490, 2013). "This may be explained by the fact that BRAF mutations are acquired during the early stages of tumor progression, for example during radial to vertical growth phase, resulting in a larger portion of the primary tumor with the mutation." (PMID 23951556, 2013). "Importantly, administration of targeted therapy inhibiting mutant BRAF to BRAF wild-type patients has been shown not only to have absence of benefit, but can also cause a growth advantage in those tumor cells by paradoxically stimulating the MAPK pathway." (PMID 23951556, 2013). "Moreover, BRAF mutation was associated with extrathyroidal extension and advanced tumor stage in PTCs." (PMID 23883275, 2013). "The higher prevalence of age-related thyroid diseases, such as HT or longer exposure to endocrine disrupters and thyroid toxic agents, may affect the prevalence of BRAF mutations in elderly subjects as well as the sensitivity of BRAFV600E as a tumor marker." (PMID 24267957, 2013). "Mutated BRAF also promotes the secretion of IL-1α and IL-1β, innate inflammatory mediators which can drive tumor cells to protect themselves from immune attack by up-regulating molecules that inhibit the function of anti-tumor lymphocytes." (PMID 24829749, 2013). "For patients with BRAF-mutated tumours, there was a suggestion of harm with panitumumab." (PMID 23725851, 2013). "Thus, for tumors harboring NRAS or BRAF mutations, activation of this pathway is thought to play a key role in driving tumor growth." (PMID 23673558, 2013). "Moreover, we did not identify significantly improved progression-free survival in tumours with gene-fusions or BRAF V600E mutation." (PMID 23947815, 2013). "Further testing of the patient’s original tumor revealed a V600E BRAF mutation." (PMID 23470635, 2013). "The question of whether tumor KRAS/BRAF mutation status may be a reliable biomarker for the purpose of selecting high-risk patients to anti-EGFR therapy, however, remains elusive." (PMID 23226389, 2012). "Given the varied clinical responses of patients to BRAF inhibitor therapy, these data suggest that additional studies to determine possible associations between clinical outcomes and intra- and inter-tumor heterogeneity could prove fruitful." (PMID 22235286, 2012). "Somatic mutations of PIK3CA may coexist with either KRAS or BRAF mutations within the same tumor, but KRAS and BRAF mutations appear to be mutually exclusive." (PMID 22931052, 2012). "Our observation that KRAS/BRAF wild-type and mutated tumors had overlapping kinase activity profiles is consistent with the increasing recognition of tumor heterogeneity, reflected in disparate mutation status, as determinant of variable response to anti-EGFR antibody therapy." (PMID 23226389, 2012). "Tumor cells exhibited wild-type alleles of BRAF and c-Kit as revealed by RT-PCR." (PMID 22289880, 2012). "Although CIMP, MSI, and BRAF mutation may be present in the same tumor, there are also clearly distinct clinical outcomes observed across the 3 categories." (PMID 22792460, 2012). "Mutational study of the tumor revealed a double BRAF mutation on V-600E and V600M." (PMID 23031422, 2012).